LEP (leptin)
Diseases named in the same sentence as LEP in open-access papers (continued):
Sharing a sentence is not in itself a finding about the gene and the disease.
Obesity (continued). "High amounts of fat in the body have been suggested to activate thermogenesis to counteract further obesity, and leptin has been assumed to mediate this signal (although leptin is actually not thermogenic)." (PMID 37499977, 2023). "Only one study observed significantly decreased levels of TNF‐α and leptin and increased adiponectin concentration in the HIIT group, which has been associated with a lower risk of obesity and breast cancer mortality." (PMID 37587859, 2023). "Individuals with obesity have higher adiposity levels, which are the substrate for producing leptin; this results in increased leptin levels and heightened sympathetic nerve activity, which is associated with elevated BP28,86." (PMID 37117457, 2023). "The highest AUCROC values identifying obesity were found for insulin, C-peptide, leptin and HOMA-IR values." (PMID 37373485, 2023). "Adiponectin is another important adipokine and in contrast to leptin, its expression levels are decreased in individuals with obesity." (PMID 38068717, 2023). "Obesity and excess adipose tissue lead to increased production of free fatty acids, leptin, and cytokines, and these metabolic abnormalities are associated with decreased physical activity and increased triglycerides, leading to hyperinsulinemia and IR42." (PMID 36922570, 2023). "Deletion of the Dgat1 gene (Dgat1−/−) increased energy expenditure in mice, improved leptin and insulin sensitivity, and improved resistance to diet-induced obesity and NAFLD." (PMID 36817150, 2023). "In obesity, where there is an elevated triacylglycerol level and an increased fat mass, leptin is elevated." (PMID 36766750, 2023). "Circulating leptin is actually elevated in obese people due to leptin resistance, and regarded as a uremic toxin, frequently exacerbates the progression of obesity-related nephropathy." (PMID 37630806, 2023). "Leptin and leptin receptor are well-documented mediators of obesity through their role in appetite suppression; however, their potential role in FMC was only recently explored." (PMID 37626804, 2023). "During obesity, leptin resistance occurs due to leptin’s inability to reach the target cells, reduced LepR gene expression or disturbed LepR signaling." (PMID 38136564, 2023). "Leptin and adiponectin, the primary adipokines from adipocytes, are known to impact obesity and insulin sensitivity on a systemic level." (PMID 37513964, 2023). "Hormones that control hunger, satiety, obesity, glucose, and maintain weight include leptin, ghrelin, cholecystokinin (CCK), oxyntomodulin (OXM), glucagon-like receptor-1 (GLP-1), insulin-like peptide-5 (INSLP-5), and peptide YY (PYY)." (PMID 36790719, 2023). "Mice that lack leptin and its functional receptor (LepRb), that is ob/ob and db/db mice, respectively, develop hyperphagia, obesity, and type 2 diabetes." (PMID 36834794, 2023). "In sum, deficiency for CerS6 in POMC neurons attenuates the diet-dependent effects on mitochondrial morphology in male mice, increases POMC neuron leptin sensitivity, and improves the insulin-dependent regulation of glucose metabolism in obesity." (PMID 38016943, 2023). "Here, we suggest that adiponectin and leptin, protein hormones secreted by white adipose tissue explain the relationship between obesity and cognitive decline." (PMID 37363537, 2023). "Taken together, these data show that our model of diet-induced obesity effectively induced weight gain, increased circulating leptin and glucose intolerance in mice, and that VSG improved glucose tolerance in both HDM- and saline-challenged obese mice." (PMID 36926031, 2023). "Western diet and obesity can promote systemic chronic inflammation with increased proinflammatory cytokines such as leptin." (PMID 37173907, 2023). "For example, IL-6 is known to be increased in obesity, shares signaling pathways with leptin, and can have synergistic effects on T cells." (PMID 37276236, 2023).
Obesity (continued). "Another hormone involved in obesity as well as in ASD development is leptin, found to be elevated in the plasma of obese people, and upon placental dysfunction during pregnancy." (PMID 37891743, 2023). "Obesity can increase leptin secretion, and it can regulate biliary lipid metabolism to promote the elimination of excess cholesterol stored in adipose tissue." (PMID 37004051, 2023). "Some authors believe leptin resistance develops in response to obesity, while some findings suggest that obesity develops in response to aging-associated leptin resistance." (PMID 38068822, 2023). "Nevertheless, in obesity, a decreased sensitivity to leptin occurs; thus, leptin levels are paradoxically increased, likely due to adipose tissue inflammation." (PMID 36674661, 2023). "The findings discussed in the present review suggest that moderate exercise is capable of improving hypothalamic inflammation in obesity, restoring leptin and insulin sensitivity, and exerting positive effects on food intake and body weight." (PMID 36829858, 2023). "To elucidate the correlation between SLC35D3 and obesity, we examined Slc35d3 expression in adipose tissues from obese mice, including leptin deletion-induced obese (ob/ob) mice and diet-induced obesity (DIO) mice." (PMID 37996411, 2023). "Diet-induced obesity exacerbates leptin signaling, and this pathway plays a prominent role in HFD-induced hypothalamic responses, promoting an increase in the number of microglia." (PMID 36869375, 2023). "Whereas, it protects memory and cognitive function by preventing neurodegeneration and obesity-induced leptin resistance." (PMID 37363537, 2023). "In line with our study, this is accompanied by a reduction in BAT mass and plasma leptin levels in obesity." (PMID 37138269, 2023). "On the contrary, adiponectin, an anti-inflammatory cytokine, regulates metabolic processes and the adiponectin-leptin ratio serves as a marker of obesity-related inflammation." (PMID 38260160, 2023). "The study revealed that thermosensitive hydrogels are suitable for loading multimodality therapeutic agents to enhance the bioactivity of leptin for obesity therapy." (PMID 37998968, 2023). "Since obesity is linked to chronic inflammatory processes, it is very encouraging that KPE effectively prevented HFD-induced increases in leptin concentrations in our study." (PMID 37691744, 2023). "Taken together, these findings suggest that states of metabolic endotoxemia and inflammation induced by high-fat diets lead to increased concentrations of SOCS3, thereby leading to leptin resistance and contributing to hyperphagia and obesity." (PMID 37571301, 2023). "Baseline plasma glucose, leptin levels, diagnosis of type 2 diabetes or type of vaccine did not correlate with neutralizing capacity in individuals with severe obesity." (PMID 37169862, 2023). "Leptin, which is upregulated in obesity, has been shown to accelerate destruction of ꞵ-cells, while adiponectin, that is downregulated in obesity, was shown to protect ꞵ-cells from apoptosis." (PMID 37919779, 2023). "Although leptin is supposed to resist the weight gain, obesity usually leads to increased secretion of leptin." (PMID 37266440, 2023). "Compared with the normal group, the leptin content in the M group was significantly increased, indicating that obesity led to the compensatory increase of leptin in mice, leading to leptin resistance." (PMID 37569125, 2023). "A previous study also reported that marine collagen from skate reduced the leptin level in an animal model of obesity." (PMID 36794279, 2023). "The plasma levels of acylated ghrelin, another hormone that regulates hunger in opposition to leptin, decreased in patients with insulinoma, probably due to hyperinsulinemia and obesity in the patients." (PMID 37190276, 2023). "As carob showed its anti-obesity effect, it possibly diminished these obesity-associated HDL-C-lowering factors, especially leptin levels, thereby inducing the HDL-C to rise." (PMID 38004588, 2023).
Obesity (continued). "Type 2 diabetic mice (db/db mice) are leptin resistant, developing obesity and several metabolic complications." (PMID 37571368, 2023). "Leptin is an adipokine secreted in proportion to adipocyte mass and is therefore increased in obesity." (PMID 37276236, 2023). "Excessive androgens prompt obesity by reducing the communication between the hypothalamic nucleus and brown adipose tissue, and decreasing the function of leptin." (PMID 37900128, 2023). "Firstly, insufficient sleep impacts the secretion of appetite-regulating hormones like leptin and ghrelin, potentially contributing to obesity." (PMID 37958033, 2023). "In obesity, there is leptin resistance, resulting in decreased sensitivity to its signals, which can lead to overeating and weight gain." (PMID 37629396, 2023). "In obesity, levels of leptin are higher and transport across the BBB is altered, while activated inflammatory pathways promote central leptin resistance." (PMID 37446161, 2023). "Leptin signaling is dysregulated in obesity, however, where appetite remains elevated despite high levels of circulating leptin." (PMID 37002197, 2023). "It was shown that the ROC curve for insulin lies below the ROC curve for leptin, and thus leptin was the indicator with the highest discriminant value for obesity." (PMID 37373485, 2023). "Change in appetite behavior due to an increase in ghrelin and a decrease in leptin level promotes obesity, metabolic syndrome, lesser physical activity, and fatigue which significantly contribute to the progression of NAFLD." (PMID 37163444, 2023). "This statement is based on the fact that leptin, which is considered as an adipokine closely related to obesity, is produced proportionally to the amount of adipose tissue." (PMID 37510725, 2023). "There are different strategies to reverse states of resistance to the action of leptin, especially in obesity." (PMID 36674935, 2023). "We also elaborate on obesity-induced inflammation and its role in the altered actions of leptin during obesity." (PMID 36769012, 2023). "Inhibition of ERK1/2 blocks the appetite-inhibiting actions of leptin, and deletion of SHP-2 in POMC neurons causes mild obesity, along with an imbalance of energy homeostasis." (PMID 36674935, 2023). "Regarding the PUFAs, it has been reported that combined EPA-DHA treatment negatively affects leptin and obesity-related membrane-type MT1-MMP (MMP-14) mRNA expression in rabbit subcutaneous ASCs in vitro." (PMID 37235430, 2023). "Leptin resistance has been found to reduce satiety, leading to obesity and secondary hyperleptinemia in several obese patients." (PMID 36830844, 2023). "As such, the identification of novel molecules capable of enhancing leptin sensitivity is a critical step in the development of new therapeutic approaches to address obesity." (PMID 38027481, 2023). "Leptin is positively correlated with obesity and insulin resistance, while adiponectin shows a good ability to enhance insulin sensitivity and counteract the development of diabetes." (PMID 36790383, 2023). "Here, we show that the LepR-expressing portal neurons send GABAergic projections to a cohort of α3-GABAA receptor expressing neurons within the dorsomedial hypothalamic nucleus (DMH) for the control of leptin-mediated obesity phenotype." (PMID 37043384, 2023). "Serum leptin concentration meaningfully correlates with fat mass and is substantially elevated in patients suffering from obesity, which leads to metabolic diseases being elements of MS." (PMID 37190276, 2023). "Altered biomarkers such as leptin and hsCRP likely contribute to obesity and inflammation in this population." (PMID 37836547, 2023). "Adiponectin and leptin are the two major hormones that explain how obesity and cognitive decline are interconnected." (PMID 37363537, 2023). "Leptin, an adipokine found in higher concentrations in pregnant women with obesity, has a cumulative inhibitory effect on myometrial contractility in vitro." (PMID 37566578, 2023).
Obesity (continued). "Enhancing or sustaining the activation of SOCS3, increases obesity-induced leptin concentrations in the blood, leading to leptin resistance." (PMID 37387537, 2023). "Conversely, SHP2 overexpression in the medial basal hypothalamus (MBH) protects mice from diet-induced obesity by enhancing ERK1/2 activation by leptin." (PMID 38027481, 2023). "The hormone’s (leptin) ability to effectively reduce food intake and body weight led to its initial utility for treating obesity." (PMID 37371552, 2023). "We found a significant association between treatment-induced changes in liver enzyme levels (particularly ALT) and inflammation markers, IR, and leptin in children with obesity aged 6–9 years." (PMID 36894963, 2023). "For instance, leptin secreted by adipose stromal/stem cells isolated from women with obesity enhances the expression of epithelial-to-mesenchymal transition (EMT) and metastasis-related genes, such as serpine 1, matrix metalloproteinase 2 (MMP-2) and IL-6." (PMID 36670988, 2023). "In fact, the serum level of anti-inflammatory adiponectin clearly decreases, whereas leptin levels increase in HS compared to healthy donors, indicating the presence of a leptin resistance, which further promotes obesity." (PMID 37686829, 2023). "Since T cells have a critical role in driving inflammation and systemic glucose intolerance in obesity, we sought to determine the role of leptin signaling in this context." (PMID 37276236, 2023). "Numerous studies have reported a significant correlation between the levels of leptin, obesity, and infertility with respect to the hypothalamic–pituitary–testicular axis, the regulation of androgen levels, and the production of sperm." (PMID 38203349, 2023). "To date, little effort has been made to study the role of leptin in muscle mitochondria metabolism and its link with obesity." (PMID 38001815, 2023). "We explored the inflammatory effects of leptin/obR signaling in an obesity-related neutrophilic airway inflammation mouse model." (PMID 37488474, 2023). "Another study conducted with adolescents also demonstrated improvements in leptin concentrations, promoting a 23.0% reduction after 22 weeks of semi-intensive intervention in adolescents with obesity." (PMID 38063544, 2023). "Leptin's critical role as a signal-transducing cytokine and its known hypothalamic negative feedback loop are reasons for its potential in treating obesity." (PMID 37937009, 2023). "We systematically searched PubMed and World Health Organization (WHO) websites with the keywords obesity and dementia and compiled literature that explains how adiponectin and leptin impact obesity and cognitive decline." (PMID 37363537, 2023). "The reduced leptin action characteristic of the leptin resistance of obesity and Type 2 diabetes leads to a hyperactive adrenal axis." (PMID 38260129, 2023). "Genetic loss of leptin results in increased food intake and severe early onset obesity in both mice and humans, and administration of recombinant leptin is sufficient to restore normal body weight in this context." (PMID 37002197, 2023). "Except for the disruption of the hypothalamic structure integrity, the existence of hypothalamic resistance to various circulation hormones was found to contribute to obesity, such as leptin." (PMID 37509115, 2023). "In a moderate to high level of leptin circumstances, just as in obesity, leptin regulates ovarian steroidogenesis." (PMID 37958056, 2023). "Administration of onion peel extracts effectively reduces body fat by increasing adiponectin and decreasing leptin in a high‐fat diet (HFD)‐induced obesity model." (PMID 37576046, 2023). "Leptin levels were significantly higher with the appearance of obesity (O) (p = 0.003) even if obesity was present with diabetes (OD) (p < 0.001) when compared to the control (C) group." (PMID 36901837, 2023).
Obesity (continued). "Measuring Leptin level is a hot topic now, and more topics are focusing on its measurement as early childhood obesity, early childhood developmental assessment scores." (PMID 37744450, 2023). "Although currently such a factor remains to be identified, this model is reminiscent of global DGAT1 knockout mice, which exhibit increased energy expenditure, enhanced glucose metabolism, protection from diet-induced obesity, and increased leptin sensitivity." (PMID 37782317, 2023). "Adipokines such as leptin and adiponectin secreted by adipose tissue regulate insulin resistance, appetite, and obesity." (PMID 36843597, 2023). "Hypothalamic LepRb neurons that control energy balance represent important potential targets for obesity therapy, but the cell types most important for the control of food intake and body weight by direct leptin action remain to be defined." (PMID 37581939, 2023). "Inflammation in obesity disrupts the leptin signalling pathway to inhibit its protective effects on the brain." (PMID 37086380, 2023). "Factors induced by obesity, such as the effects of systemic inflammation, increased aromatase activity, and leptin production, have all been suggested to interfere with testosterone production." (PMID 38089610, 2023). "In situations of obesity, “leptin resistance” occurs, in which the circulating concentrations of this hormone increase." (PMID 37445834, 2023). "Recently, in mammary tissues of a rat model of breast cancer driven by diet-induced obesity, increased expression of the leptin/leptin receptor (Ob/ObR) along with signaling activation were found." (PMID 37509120, 2023). "People affected by obesity have higher circulating levels of leptin, but reduced hypothalamic sensitivity to its anorectic action, resulting in increased inflammation and fibrosis." (PMID 37299398, 2023). "Obesity is a growing threat to human health worldwide, leading to severe metabolic complications, including diabetes mellitus, insulin and leptin resistance, and other metabolic disorders." (PMID 36982473, 2023). "Nonetheless, our case report is the first that demonstrates the beneficial effects of NB, together with metformin, in an individual with severe obesity due to a defective leptin-melanocortin pathway." (PMID 36876127, 2023). "Obesity usually increases circulating CD4+ T cell levels via leptin-mediated upregulation of major histocompatibility complexes-II (MHC-II, 80)." (PMID 37266440, 2023). "Leptin, in particular, has been extensively investigated as a potential mediator of obesity-related cancers." (PMID 37954072, 2023). "Stimuli-responsive thermosensitive carriers for therapeutic agents to enhance the bioactivity of leptin for obesity therapy." (PMID 37998968, 2023). "Ongoing research is addressing leptin resistance, which needs to be overcome in order to also utilise leptin’s potential in the therapy of obesity." (PMID 37239098, 2023). "In our clinical study, we examined metabolic and inflammatory parameters, kidney function, and leptin levels among patients afflicted with hypertension, obesity, type 2 diabetes, and cardiovascular diseases." (PMID 36901837, 2023). "As far as adipokines are concerned, it is known that, in obesity, adiponectin decreases, and leptin increases." (PMID 37686769, 2023). "In this study, we measured DNA methylation of the promoter for the obesity-regulated gene LEP, encoding leptin, in hematopoietic cells from ICUS, CCUS and MDS patients and healthy controls." (PMID 37237325, 2023). "A study that evaluated FABP2, LEPR, LEP and FTO polymorphisms in individuals who underwent RYGB found that the %EWL was higher in patients with obesity carriers of the LEP variant rs1137101, 12 and 24 months after surgery." (PMID 37129798, 2023). "Elevated levels of leptin can potentially accelerate the progression of obesity-related lung cancer through the activation of the STAT1- solute carrier family 7 member 11 (SLC7A11) pathway, which mediates ferroptosis." (PMID 37943609, 2023).